SHPRH (SNF2 histone linker PHD RING helicase)
Description:
E3 ubiquitin-protein ligase involved in DNA repair. Upon genotoxic stress, accepts ubiquitin from the UBE2N-UBE2V2 E2 complex and transfers it to 'Lys-164' of PCNA which had been monoubiquitinated by UBE2A/B-RAD18, promoting the formation of non-canonical poly-ubiquitin chains linked through 'Lys-63'.
Synonyms: KIAA2023; FLJ90837; bA545I5.2; RAD5
Tractability: PROTAC: ubiquitination databases record sites on it; its protein half-life has been measured.
Target class: Enzyme; Transferase
Gene: Protein-coding gene on chromosome 6 (145,864,245 to 145,964,423, reverse strand). Ensembl gene ENSG00000146414.
Subcellular location (Human Protein Atlas): Nuclear membrane; Nucleoplasm; Cytosol
Pathways (Reactome):
Metabolism of proteins: E3 ubiquitin ligases ubiquitinate target proteins
Gene Ontology:
Molecular function: protein binding; ubiquitin protein ligase activity; ubiquitin protein ligase binding; ubiquitin-protein transferase activity; ATP binding; DNA binding
Biological process: DNA damage response; protein polyubiquitination; protein ubiquitination; nucleosome assembly
Cellular component: nucleoplasm; nucleosome
Genetic constraint (gnomAD): Loss-of-function variants: 91 observed, 182.13 expected, observed/expected ratio (o/e) 0.5, 90% interval 0.42 to 0.6. The upper end of that interval is the gene's LOEUF score, 0.6, which puts it in group 2 of 6, group 1 being the genes least tolerant of losing a copy. Missense variants: 1,606 observed, 1,992.9 expected, observed/expected ratio (o/e) 0.81, 90% interval 0.77 to 0.84. Synonymous variants: 692 observed, 679.84 expected, observed/expected ratio (o/e) 1.02, 90% interval 0.96 to 1.08.
Homologues: Orthologues: chimpanzee SHPRH (99% identical), macaque SHPRH (98% identical), pig SHPRH (91% identical), rabbit SHPRH (90% identical), dog SHPRH (89% identical), guinea pig SHPRH (86% identical), mouse Shprh (86% identical), rat Shprh (85% identical), tropical clawed frog shprh (67% identical), zebrafish shprh (62% identical), Caenorhabditis elegans T05A12.4 (17% identical). Paralogues in human: CHD7 (13% identical), CHD9 (12% identical), CHD5 (12% identical), CHD8 (12% identical), CHD6 (12% identical), CHD4 (12% identical), CHD1 (12% identical), SMARCA4 (12% identical), CHD3 (11% identical), SMARCA2 (11% identical), CHD2 (11% identical), EP400 (11% identical), and 18 more.
Diseases named in the same sentence as SHPRH in open-access papers:
SHPRH is named in the same sentence as 36 diseases in open-access papers, as found by Europe PMC text mining. Sharing a sentence is not in itself a finding about the gene and the disease. The quoted sentences say what the papers report.
glioblastoma (36 papers, 2018 to 2026). The most malignant astrocytic tumor (WHO grade IV). "Studies found that a circRNA from the SNF2 histone linker PHD RING helicase (SHPRH) encodes a novel protein called SHPRH-146aa, and both circ-SHPRH and SHPRH-146aa are abundantly expressed in the normal human brain but downregulated in glioblastoma." (PMID 36139159, 2022). "Compared with other peptides encoded by circRNAs, such as circPPP1R12A‐73aa in colon cancer and SHPRH‐146aa in glioblastoma, the protein encoded by circARHGAP35 is remarkably large (1289 aa)." (PMID 34258149, 2021). "In another study, the overexpression of protein SHPRH-146aa encoded by SNF2 histone linker PHD RING helicase (SHPRH) gene was found to reduce the malignant behavior and tumorigenicity of glioblastoma cells (U251 and U373) in vivo and in vitro." (PMID 33614648, 2021). "Another protein-translating circRNA is circSHPRH, which is downregulated in 81% of glioblastoma samples, and encodes a functional protein SHPRH-146aa." (PMID 30111313, 2018). "Another study focused on SHPRH-146aa, which is encoded by circ-SHPRH, and showed that the SHPRH-146aa expression was significantly downregulated in 60 glioblastoma samples compared with their adjacent normal tissues." (PMID 30483132, 2018). "Furthermore, recent studies of a novel protein encoded by a circular RNA form of SHPRH (circ-SHPRH) has identified it as having a tumor suppressive function in glioblastoma." (PMID 38890444, 2024). "As introduced above, the novel protein SHPRH-146aa, which was encoded by the circ-SHPRH, regulates glioblastoma tumorigenicity via stabilizing the full-length SHPRH (SNF2 histone linker PHD RING helicase) protein by inhibiting its ubiquitin-mediated degradation." (PMID 35071227, 2021). "The FBXW7-185aa encoded by circ-FBXW7 can inhibit the proliferation and cell cycle acceleration of glioma, and the circular SHPRH as well as circular AKT3 could encode tumor-suppressed peptides in glioblastoma." (PMID 35281715, 2021). "In glioblastoma, circSHPRH encoded a peptide named SHPRH-146aa." (PMID 33643900, 2020). "For example, circ-SHPRH encodes SHPRH-146aa, which inhibits malignant cell proliferation in glioblastoma (GBM)." (PMID 41181701, 2025). "SHPRH-146aa is a circORF-encoded peptide that has the potential to serve as a prognostic or diagnostic biomarker for glioblastoma (GBM)." (PMID 39123386, 2024). "For example, SHPRH-146aa limits the PCNA protein level and thereby glioblastoma cell proliferation by protecting full-length SHPRH, which is the ubiquitin ligase E3 of PCNA." (PMID 41261216, 2026). "In human glioblastoma, SHPRH-146aa, which was produced from the overlapping genetic codes of circ-SHPRH, acts as a tumor suppressor." (PMID 38321530, 2024). "A study had shown that overexpression of SHPRH-146aa in glioblastoma cells reduces its malignant behavior and tumorigenicity in vitro and in vivo." (PMID 38282862, 2024). "When SHPRH-146aa is upregulated in glioblastoma cells of the U251 and U373 strains, these cells behave less malignantly and are less tumorigenic both in vitro and in vivo." (PMID 37243750, 2023). "Circ-SHPRH and SHPRH-146aa both have high expression levels in healthy human brain tissue but are downregulated in glioblastoma-derived samples." (PMID 37243750, 2023). "Overexpression of SHPRH-146aa lowers the malignant behavior and tumorigenicity of U251 and U373 glioblastoma cells in vitro and in vivo." (PMID 35883576, 2022). "In normal human brains, both circ-SHPRH and SHPRH-146aa are abundantly expressed, however in glioblastoma they are suppressed." (PMID 35883576, 2022). "Recently, it has been found that the overexpression of SHPRH-146aa reduces the malignancy of glioblastoma cells with increased levels of SHPRH-146aa, and glioblastoma patients have increased survival time." (PMID 35223470, 2022). "SHPRH-146aa, derived from circ-overlapping SHPRH’s genetic codes, functions as a tumor suppressor in human glioblastoma." (PMID 35883576, 2022).
glioblastoma (continued). "The overexpression of SHPRH-146aa in U251 and U373 glioblastoma cells weakens their malignant behavior and tumorigenicity in vitro and in vivo." (PMID 33816529, 2021). "Both circ-SHPRH and SHPRH-146aa are amply expressed in normal human brains and decreased in glioblastoma." (PMID 33816529, 2021). "Circ-SHPRH and SHPRH-146aa are highly expressed in normal human brain tissue and downregulated in glioblastoma." (PMID 32019587, 2020). "Overexpression of SHPRH-146aa in U251 and U373 glioblastoma cells can reduce the degree of malignancy and tumorigenicity both in vivo and vitro." (PMID 33324638, 2020). "In glioblastoma, circ-SHPRH can be translated into SHPRH-146aa, which is involved in the occurrence and development of tumors of the central nervous system by regulating the protein ubiquitination pathway." (PMID 33324638, 2020). "Both circ-SHPRH and SHPRH-146aa were highly expressed in normal human brains and are down-regulated in glioblastoma." (PMID 32061256, 2020). "SHPRH-146aa overexpression in U251 and U373 glioblastoma cells reduces their malignancy and tumorigenicity in vitro and in vivo." (PMID 32019587, 2020). "Full-length SHPRH then suppressed glioblastoma progression by inducing proliferating cell nuclear antigen (PCNA) ubiquitination as an E3 ligase." (PMID 33643900, 2020). "A novel protein derived from circ-SHPRH was also found to be abundantly expressed in human brains and dysregulated in glioblastoma." (PMID 31861825, 2019). "Overexpression of SHPRH-146aa in glioblastoma cells reduces their malignant behavior and tumorigenicity both in vitro and in vivo, further supporting the idea that SHPRH possess tumor suppressor functions." (PMID 31434570, 2019). "For example, FBXW7–185aa translated from circ-FBXW7 and SHPRH-146aa translated from circ-SHPRH are tumor suppressors in glioblastoma." (PMID 30112184, 2018). "Both circSHPRH and SHPRH-146aa were downregulated in glioblastoma, which suppress cell proliferation and tumorigenesis." (PMID 30111313, 2018). "Cancer patients with higher SHPRH-146aa expression had a longer survival time than those with lower SHPRH-146aa expression in glioblastoma patient samples." (PMID 30483132, 2018). "Prolonged survival was observed in glioblastoma patients with elevated SHPRH-146aa levels." (PMID 38282862, 2024). "However, while it was suggested that this protein operated by protecting the full-length SHPRH protein from degradation, no further investigation was done on the function of full-length SHPRH itself in glioblastoma." (PMID 38890444, 2024). "Circ‐SHPRH is highly expressed in normal human brain cells but is reduced in glioblastoma." (PMID 31556152, 2020). "The result suggested SHPRH-146aa is a prognostic marker for glioblastoma in clinics." (PMID 30483132, 2018). "The study showed that SHPRH-146aa could serve as a prognostic marker for glioblastoma." (PMID 36139159, 2022). "Moreover, circ-SHPRH and SHPRH-146aa were lowly expressed in glioblastoma and overexpressed SHPRH-146aa could increase parental gene SHPRH (SNF2 histone linker PHD RING helicase) expression to downregulate its tumorigenicity in vitro and in vivo." (PMID 36091137, 2022). "Circ-SHPRH encodes a 17 kDa peptide with a length of 146 amino acids, named SHPRH-146aa, which could protect its parental gene SNF2 histone linker PHD RING helicase (SHPRH) from degradation via the ubiquitin proteasome and functions as an inhibitor of glioblastoma." (PMID 34869349, 2021). "In addition, recent studies show that some circRNAs are translated, including circ-SHPRH, which generates a 17 kDa SHPRH-146aa protein that acts as a novel tumor suppressor protein and a protective decoy for its full-length SHPRH protein in glioblastoma." (PMID 30545127, 2018).
glioma (27 papers, 2019 to 2025). A benign or malignant brain and spinal cord tumor that arises from glial cells (astrocytes, oligodendrocytes, ependymal cells). "Similar to this, circ-SHPRH encodes SHPRH-146aa, a tumor-suppressive protein that prevents full-length SHPRH from degrading and thereby stops the growth of gliomas." (PMID 40896358, 2025). "SHPRH-146aa, a protein encoded by circ-SHPRH, can protect SHPRH from degradation by the ubiquitin‒proteasome and reduce the malignant behavior of glioma cells in vivo and in vitro." (PMID 37305675, 2023). "For example, circ-SHPRH suppresses tumorigenesis of glioma cells by encoding the protein SHPRH, and the novel protein circFAM188B-103aa, encoded by circFAM188B promotes proliferation, but inhibits differentiation, of chicken skeletal muscle satellite cells." (PMID 35863430, 2022). "For example, circ-SHPRH is reported to encode the protein SHPRH-146aa, protect full-length SHPRH from degradation by the ubiquitin proteasome, and ultimately inhibit glioma tumorigenesis." (PMID 33634138, 2021). "SHPRH-146aa is encoded by circ-SHPRH, which can protect full-length SHPRH from degradation by the ubiquitin proteasome and inhibit glioma tumorigenesis." (PMID 33836754, 2021). "Recent study has revealed a tumor suppressive protein encoded by the circular form of the SHPRH gene in glioma tumorigenesis." (PMID 30925892, 2019). "The circular transcript of the SNF2 histone linker PHD RING helicase (SHPRH) gene encodes a fully functional protein, 17kDa, termed circ-SHPRH, which suppresses the tumor transformation of glioma cells." (PMID 31781482, 2019). "It has been reported that circ-SHPRH also encodes a protein called SHPRH-146aa in glioma." (PMID 37305675, 2023). "Importantly, IRES and ORF are the two important components of circ-SHPRH, encoding SHPRH-146aa, inhibits the proliferation and tumorigenesis in glioma." (PMID 36064939, 2022). "Circular SHPRH could encode a 17 kDa protein and suppresses glioma tumorigenesis." (PMID 36861189, 2023). "SHPRH-146aa protected SHPRH from ubiquitin-mediated proteasomal degradation and acted as an E3 ligase, resulting in suppression of glioma tumorigenesis and proliferation." (PMID 38075205, 2024). "Overexpression of SHPRH-146aa can reduce the malignant behavior and tumorigenicity of glioma in vitro and in vivo." (PMID 37305675, 2023). "The results showed that circ-SHPRH is a tumor suppressor in glioma and a possible biomarker for this type of cancer." (PMID 37305675, 2023). "Compared with normal tissues, the expression levels of circ-SHPRH and SHPRH-146aa were both downregulated in gliomas." (PMID 37305675, 2023). "Some studies have confirmed that circ-SHPRH is under expressed in many kinds of cancer, such as gastric cancer, glioma, and cholangiocarcinoma." (PMID 37305675, 2023). "The study also found that the upregulation of circ-SHPRH can suppress the growth and cloning ability of glioma cells and promote the apoptosis of glioma cells." (PMID 37305675, 2023). "Another circRNA, circSHPRH, inhibits glioma cell proliferation via translating the SHPRH-146aa, which prevents SHPRH protein from being degraded." (PMID 36030248, 2022). "For example, circ-SHPRH regulated the expression of SHPRH-146aa protein, which protected SHPRH from degradation by the ubiquitin proteasome and ultimately inhibited glioma tumorigenesis." (PMID 36133810, 2022). "Both circ-SHPRH and its transcripts are highly expressed in normal human brain cells, participating in the inhibition of central nervous system cancers through the ubiquitin-proteasome pathways triggered by SHPRH." (PMID 35223470, 2022). "The downregulation of SHPRH-146aa in glioma cells results in intensified carcinogenesis and a decreased expression of the full-length SHPRH protein." (PMID 32781555, 2020). "A study revealed the presence of the downregulated circRNA circ-SHPRH in gliomas, which translates a new 17 kDa protein that named SHPRH-146aa by using overlapping genetic codes." (PMID 30626395, 2019).
glioma (continued). "In addition, circ-SHPRH and circ-FBXW7 and their encoded proteins are highly expressed in normal brains but downregulated in gliomas." (PMID 33627631, 2021). "Furthermore, the circRNA-derived protein SHPRH-146aa suppresses glioma tumorigenesis by protecting full-length SHPRH from degradation by the ubiquitin–proteasome." (PMID 33947841, 2021). "has been reported that circ-SHPRH encodes the protein SHPRH-146aa, which acts as a decoy, protecting the SHPRH protein from ubiquitin-mediated degradation by retinoic acid-regulated nuclear matrix-associated protein (DTL), thereby inhibiting glioma development." (PMID 41267993, 2025). "Similarly, circ-SHPRH sponges miR-331-3p and miR-338-5p to inhibit cell proliferation and migration in non-small cell lung cancer, and it can generate a peptide SHPRH-146aa to suppress glioma tumorigenesis." (PMID 37509138, 2023). "Exemplified by circ-SHPRH, a protein templates driven by internal ribosome entry site (IRES) elements acts as the SHPRH protein decoy to prevent DTL-mediated ubiquitination degradation, thereby inhibiting glioma development." (PMID 35366893, 2022). "These circRNAs have open reading frames that encode functional proteins with the help of internal ribosome entry sites, and their corresponding proteins SHPRH-146aa and FBXW7-185aa can inhibit the proliferation of glioma cells." (PMID 33627631, 2021). "Similarly, stable SHPRH, as an E3 ligase, ubiquitinated proliferating cell nuclear antigen (PCNA), thus inhibiting glioma cell proliferation and tumorigenicity." (PMID 34106407, 2021).
hepatocellular carcinoma (6 papers, 2020 to 2024). A malignant tumor that arises from hepatocytes. "In addition, overexpression of circ-SHPRH caused increased expression of caspase-3 and caspase-9 in hepatoma cells, further enhancing apoptosis." (PMID 37305675, 2023).
colon cancer (4 papers, 2021 to 2024). "In ovarian cancer, germline mutation of SHPRH is associated with a moderate-to-high risk of developing ovarian cancer, while in colon cancer, SHPRH has been shown to inhibit Wnt signaling." (PMID 38890444, 2024). "Whereas axitinib targeted the ubiquitin ligase SHPRH to increase ubiquitination and proteasome-mediated degradation of β-catenin, nitazoxanide targeted PADI2 to increase citrullination and degradation of β-catenin in colon cancer cells." (PMID 34440153, 2021).
Fanconi Anaemia (3 papers, 2016 to 2024). "Surprisingly, guides targeting the fork reversal factors (SMARCAL1, HLTF, ZRANB3, SHPRH) or components of the Fanconi Anaemia pathway were neither enriched nor depleted, despite previous studies suggesting a genetic interaction between some of these factors and PRIMPOL in transformed cell lines." (PMID 37971291, 2024).
ovarian carcinoma (3 papers, 2007 to 2024). A malignant neoplasm originating from the surface ovarian epithelium. "Interestingly, the SHPRH gene is mutated in a number of cancer cell lines, including those from melanomas and ovarian cancers, which indicates that SHPRH function is an important deterrent to mutagenesis and carcinogenesis in human cells." (PMID 17936713, 2007).
neuroblastoma (2 papers, 2024). Neuroblastoma (NB) is the most common solid, extracranial childhood tumor. "In line with this, our study demonstrated, through qRT-PCR and WB, that SHPRH-146aa overexpression significantly increased NFKBIA expression in neuroblastoma cells." (PMID 38282862, 2024). "This study aimed to elucidate the role and molecular interactions of circSHPRH and its peptide derivative SHPRH-146aa in the pathogenesis of neuroblastoma (NB)." (PMID 38282862, 2024). "In the context of NB models, SHPRH-146aa exhibited a notable inhibitory effect on malignant cell behaviors, underscoring its potential as a therapeutic agent in halting neuroblastoma progression." (PMID 38282862, 2024).
colitis (1 paper, 2024). Inflammation of the colon. "Therefore, among all the molecular targets of our miRNA candidates, POU2F1, SOCS1, and circ-SHPRH are better characterized for their involvement in colitis-associated CRC." (PMID 38891888, 2024). "The circRNA/miRNA/mRNA competitive endogenous RNA (ceRNA) network analysis showed that the candidate miRNAs were connected to well-known colitis-associated CRC ACVR2A, SOCS1, IGF2BP1, FAM126A, and CCDC85C mRNAs, and circ-SHPRH circRNA." (PMID 38891888, 2024).
colorectal adenocarcinoma (1 paper, 2024). The most common type of colorectal carcinoma. "This revealed that SHPRH was mutated in 2.4% (251/10443) of all samples profiled, with endometrial carcinoma (11.6%), cutaneous melanoma (5.9%), colorectal adenocarcinoma (4.9%) and stomach adenocarcinoma (4.1%) having the highest mutation rate other than lung cancer (LUAD = 3.9%)." (PMID 38890444, 2024).
endothelial dysfunction (1 paper, 2025). In vascular diseases, endothelial dysfunction is a systemic pathological state of the endothelium (the inner lining of blood vessels) and can be broadly defined as an imbalance between vasodilating and vasoconstricting substances produced by (or acting on) the endothelium. "Furthermore, wound-healing assays revealed that the protective effects of UBE2N OE on sunitinib-induced endothelial dysfunction were reversed by inhibition of RNF8 or RNF168 but not HLTF and SHPRH." (PMID 39895626, 2025).